ORAI1 (ORAI calcium release-activated calcium modulator 1)
Diseases named in the same sentence as ORAI1 in open-access papers (continued):
Sharing a sentence is not in itself a finding about the gene and the disease.
cancer (continued). "As a general trend, there are many reports that mRNA transcription and protein expression of Orai1 are more strongly expressed in cancer cells than in normal cells regardless of cancer type." (PMID 37759164, 2023). "Recently, studies also reported that Orai remodelling was happened in cancer cell through Orai1 and Orai3 tetramer replacing Orai1 tetramer and did not need STIM1 activation." (PMID 36128650, 2022). "However, in several cancer types, it remains unexplored how Ca2+ entry via the STIM1/Orai1 machinery affects the various cell cycle effectors, either directly via Ca2+-binding proteins or indirectly via transcription factors, Ras/ERK, or PI3K/Akt pathways." (PMID 36612099, 2022). "However, in this cancer cell line, there is a direct interaction of the N- and C-termini of SPCA2 with Orai1 at the cell surface, which controls EMT." (PMID 36612099, 2022). "Orai1 channel is involved in SOCE and CCE in several types of cancer cells." (PMID 34204608, 2021). "In turn, silencing of Orai1 and 2 with SOCE chemical inhibitors and siRNAs inhibits calcium uptake and suppresses cancer cell proliferation, colony formation, and migration in association with inhibition of the Akt/mammalian target of rapamycin (mTOR)/nuclear factor κB (NF-κB) pathway." (PMID 33511135, 2020). "The overexpression of ORAI1 and STIM1 in tumor cells contributes to cancer growth." (PMID 32015442, 2020). "Studies also illustrated that ALDH1+ cancer stem cells population in non-tumorigenic oral epithelial cells is increased by expressing ectopic Orai1, which enhances OSCC metastatic potentials." (PMID 32280305, 2020). "Although more specific Orai1 blockers are certainly required to avoid off-target effects, targeting endothelial SOCE could represent an alternative strategy to fight cancer." (PMID 31416282, 2019). "Recently, an increase in SOCE, related to the up‐regulation of Stim1, Orai1 or TRPC1 expressions, has been observed in several different kinds of tumours 6, 24, 30, indicating SOCs are the potential therapeutic target for treatment of cancers." (PMID 27878958, 2017). "Hence, EGCG can be considered an epigenetic regulator of the key players accomplishing SOCE in murine CD4+ T cells, Jurkat T cells and other cancer cells, i.e. STIM1/2 and Orai1." (PMID 29163766, 2017). "Therefore, in a variety of cancer types, both STIM1 and Orai1 were found to be upregulated and positively correlated to metastasis." (PMID 27417567, 2016). "ORAI1 and STIM1 regulate proliferation, apoptosis and metastasis of various cancer cells." (PMID 26789410, 2016). "For example, carboxyamidotriazole, a novel anti-cancer drug currently in clinical trials, targets a non-voltage-gated Ca2+ channel presumed to be Orai1." (PMID 24797725, 2014). "It is therefore possible that different ion channels could be involved in affecting specific SOCE profiles as TRPC, Orai1 and STIM1 that can form heteromeric complexes or other members of the TRPC or ORAI families such as Orai3 in cancer cells." (PMID 23700407, 2013). "Blocking Orai1- and STIM1-dependnet Ca2+ signaling is thus a potential strategy for cancer therapy." (PMID 23594099, 2013). "We hypothesized that this polarized membrane Ca2+ might be induced by Orai1 Ca2+ channels, the best‐known SOC channel because it regulates lots of common signaling pathways in cancer cells that are also essential for entosis, including actin polymerization, myosin contraction, and membrane blebbing." (PMID 36960682, 2023). "In addition, many reports indicate that Orai1 plays an important role in SOCE regardless of cancer type, and it is consistent that some inhibitors and knockdown of Orai1 by siRNA or shRNA reduce SOCE." (PMID 37759164, 2023). "Furthermore, various molecules that Orai1 regulates have been reported, including Ca2+ signals, extracellular signal-regulated kinase 1/2 (ERK), and protein kinase B (Akt), however, these molecules differ depending on the cancer type or the previous articles." (PMID 37759164, 2023).
cancer (continued). "The inhibition of Orai1 function in human tongue squamous carcinoma cell lines SCC4 and HOK-16B BapT by a pharmacological approach, using the Orai1 specific small molecular blocker compound 5D, impaired self-renewal capacity and reduced migration and invasion abilities in these cancer cells." (PMID 35456011, 2022). "Furthermore, alterations in Orai1 glycosylation have been observed in cancer cells and overexpression of the enzyme β-galactoside α-2,6-sialyltransferase 1 (ST6GAL1) has been reported to play a relevant role in cancer invasiveness and metastasis." (PMID 36612199, 2022). "In the human colorectal cancer cell line HT29, the expression of Orai3, as well as Orai1, Orai2, STIM1, and TRPC1 has been shown to be enhanced as compared to the normal human colon mucosal epithelial cell line NCM460, whereas STIM2 expression was downregulated in cancer cells." (PMID 34768857, 2021). "Moreover, STIM1 and Orai1 have been reported to be overexpressed in cancer cells compared to their non-cancerous counterparts." (PMID 32235707, 2020). "However, the ability of ORAI3 but not ORAI1 silencing to attenuate EGFR phosphorylation induced by hypoxia suggested that specific events in cancer cells activated by hypoxia are fine-tuned by ORAI3." (PMID 30754719, 2019). "Consequently, some cancers upregulate STIM-1 and ORAI-1 or ORAI3 to ensure a steady supply of low- to mid-level calcium, and cancer cells may become calcium-dependent." (PMID 29758025, 2018). "The Orai1 and STIM1 inhibition could offer novel anti-cancer therapeutic strategies." (PMID 29861863, 2018). "A decrease of extracellular Ca2+ concentrations or partial inhibition of ORAI1 activity by selective blockers in the TME could obviously inhibit cancer growth by simultaneously increasing cytotoxic T Lymphocytes and natural killer cell cytotoxicity and decreasing cancer cell proliferation." (PMID 38425645, 2024). "In addition, the upregulation of ORAI1 in hypoxia determined an increase in basal Ca2+ concentration and of thapsigargin-induced SOCE, which activated the downstream NFAT4 target, known to regulate the expression of cancer-related genes involved in its hallmarks." (PMID 35806388, 2022). "While SOCE has been shown to play an essential role in various cancers, the exact contributions of expression of genes underpinning the SOCE machinery to carcinogenesis and tumor progression remains contradictory and the relevance of Orai1 per se to ESCC in patients are unknown." (PMID 24797725, 2014). "While CM4620 is not currently utilized for cancer treatment, its remarkable ability to selectively inhibit STIM1/Orai1-mediated SOCE makes it highly promising for therapeutic applications in tumors with upregulated STIM1/Orai1 expression." (PMID 37932320, 2023). "Though both cancer types exhibit SK3 and Orai1 expression, healthy tissue does not express SK3 channels." (PMID 36612099, 2022). "Then, we highlight the structure/function relationship of Orai1 and SK3, both individually and in concert, their role in the development of different types of cancer, and aspects that are not yet known in this context." (PMID 36612099, 2022). "As is the case in cancer cells, modulation of the expression of STIM1/Orai1 has differential effects in other non-cancerous cell lines." (PMID 34069353, 2021). "STIM1 and ORAI1 are two basic components of SOC as a major pathway of calcium entry in non-excitable cells, especially in the cancer cells." (PMID 33182378, 2020). "Recently, several studies have indicated a role for Orai1 and STIM1 in migration of different types of cancer and non-cancer cells." (PMID 29507531, 2018).
tumor (111 papers, 2012 to 2026). "We previously reported that high expression of Orai1 in tumor tissues is associated with poor prognosis in ESCC patients, and SOCE-mediated intracellular Ca2+ oscillations regulate cell proliferation, migration and invasion in ESCC cells." (PMID 35163685, 2022). "The transition to a more motile and invasive tumor type was accompanied by a loss of E-cadherin function, which was upregulated upon the knock-down of Orai1 in esophageal and gastric cancer." (PMID 36612099, 2022). "Taken together, these results suggest that high expression of ORAI1 is associated with tumor progression and poor clinical outcomes." (PMID 34055617, 2021). "The critical roles of STIM1 and Orai1 proteins in tumor cell migration and the underlying molecular mechanisms have been extensively studied." (PMID 31252656, 2019). "In this regard, the larger SOCE observed in tumor cells and increased expression of associated molecular players as Orai1, TRPC1 and Stim1, likely allows formation of larger Ca2+ domains near mitochondria." (PMID 28903423, 2017). "In this work, we propose a novel association between SPCA2, Kv10.1 and Orai1 involved in mediating transduction signals from TM to the BC cells that can be potentially exploited in the search of novel therapeutic targets specific to tumor tissues." (PMID 30718673, 2019). "Taking into account the importance of collagen 1 as the major component of the microenvironment in BC progression, Kv10.1 overexpression, in association at least with Orai1, constitutes a potential checkpoint of tumor progression positively regulated by the tumor microenvironment." (PMID 29872495, 2018). "In addition, activating ORAI1 through a genetically encoded light-inducible STIM1 fragment promotes tumour remission in a mouse model of DC cell-based immunotherapy." (PMID 29176619, 2017). "The discordant expression of ORAI1 in tumor tissue versus plasma suggests a unique role in tumor-host system interactions." (PMID 41461865, 2025). "In tumour animal models, knocking down the ORAI1 channel in tumour cells inhibited the secretion of PD-L1 exosomes by tumour cells, increased the number of CD8+ cells in the spleen and tumour-infiltrating CD8+ cells, and impeded tumour progression." (PMID 38302430, 2024). "The expression of ORAI1 is upregulated in glioblastoma, where it enhances tumor invasiveness and promotes migration by regulating adhesion transition." (PMID 38672434, 2024). "SGK1 phosphorylates the protein ubiquitin ligase Nedd4-2, then binds with the protein 14-3-3, and blocks its ability to ubiquinate Orai-1, resulting in increased Orai1 activity, which confers survival of tumor cells." (PMID 37345151, 2023). "The dominant negative Orai1 mutant (E106Q) inhibited the tumor sphere forming of human SCC cells (SCC4 cells) and human oral keratinocytes (HOK-16B BapT cells) according to tumor sphere formation assay." (PMID 37759164, 2023). "Still, both 2-APB treated group and Orai1 peptides treated group displayed a significantly smaller tumor volume compared to the NCL group." (PMID 36109490, 2022). "Orai1 has been reported to control tumorigenesis and tumor progression by virtue of the abnormal expression and activation, resulting in the imbalance of intracellular calcium homeostasis." (PMID 36109490, 2022). "STIM1 and Orai1 were shown to regulate tumor cell migration partially involving the mediation of the focal adhesion." (PMID 36071984, 2022). "Orai1 knockdown significantly decreased the viability of the tumor cells compared to the cells transfected with the scrambled siRNA." (PMID 36310590, 2022). "This study showed that ORAI1 expression increased with tumor progression and that it was also upregulated in CSC populations of OSCC." (PMID 36142596, 2022). "Consistent with IHC observations, ORAI1 was expressed at higher levels in CRC tumors compared with matched adjacent non-tumor tissues." (PMID 34055617, 2021).
tumor (continued). "Further evidence from the overexpression or silencing of STIM1 and Orai1 supported that in vivo anti-tumor effects of SKF-96365 or 2-APB involve the blockade of STIM1/Orai1 complex." (PMID 35008759, 2021). "Contradictorily, partial inhibition of ORAI1 in a separate study resulted in the killing of CTLs by tumor cells; more research is, therefore, warranted." (PMID 34572262, 2021). "Our study shows that GSC from patient-derived surgical tumor specimen express Orai1 and TRPC1 as well as STIM1, as do the adult neural stem cells from which GSC originate, at least in part." (PMID 34298643, 2021). "In patients with esophageal squamous cell carcinoma, the poorer overall, as well as recurrence-free survival, was characterized by high expression of Orai1 in tumor tissue." (PMID 31252656, 2019). "Next, we investigated the correlation of ORAI3/ORAI1 ratio with CRC progression by studying its variation according to tumor stages." (PMID 31010205, 2019). "The roles of STIM1 and Orai1 in carcinogenesis, tumor initiation, proliferation and metastasis have recently attracted significant attention." (PMID 31366337, 2019). "Conversely, the pharmacological blockade of Orai1 with carboxyamidotriazole, which targets both vascular endothelial cells and tumor-derived ECFC, has been probed in phase I-III clinical trials launched towards several malignancies." (PMID 31416282, 2019). "Deletion or abnormal expression of STIM1 and ORAI1 leads to congenital unprogressive myopathy, coagulopathy, T and B cell dysfunction and also affects tumor cell growth and invasion." (PMID 31426853, 2019). "The study reports an oncogenic switch in which cells, especially those exposed to tumor microenvironmental factors (here, arachidonic acid), change from homologous Orai1 complexes to more heterogeneous Orai1–Orai3 complexes by upregulating Orai3 expression." (PMID 30935064, 2019). "Overexpression of STIM1 and ORAI1 enhances the ability of some tumor cells to resist apoptosis, but leads to apoptosis of other tumor cells." (PMID 31426853, 2019). "Immunohistochemistry staining showed that Orai1 expression in tumour tissues was markedly increased compared with non‐tumour tissues." (PMID 27878958, 2017). "In tumour cells chorein up-regulates ORAI1, a Ca2+-channel accomplishing store operated Ca2+-entry (SOCE) upon stimulation by STIM1." (PMID 28743945, 2017). "Immunohistochemical analyses showed that tumor sections from FGF4-stimulated cells exhibited a marked increase in Orai1 whereas tumor sections from control and FGF4+BHQ-stimulated cells revealed no or weak staining." (PMID 27677589, 2016). "To further examine the effect of Orai1 on tumor growth in vivo, we injected the cells into nude mice and observed tumor formation." (PMID 27259269, 2016). "Tumor sphere formation assay revealed that E106Q significantly inhibits the tumor sphere forming ability of both cell lines, indicating that Orai1 is indeed essential for sustaining self-renewal capacity of CSCs." (PMID 27259269, 2016). "Orai1 expression is highly enriched in tumor spheres compared with their corresponding adherent monolayer cells." (PMID 27259269, 2016). "Ectopic Orai1 expression resulted in robust induction in tumor sphere formation, indicating the acquisition of self-renewal capacity by Orai1." (PMID 27259269, 2016). "We treated OSCC cells with the Orai1-specific small molecular blocker, compound 5D and found that the Orai1 inhibitor dramatically inhibited tumor sphere forming ability and migration at the dose of 15 μM." (PMID 27259269, 2016). "Further studies revealed that the ectopic expression of STIM1 and ORAI1 inhibits tumor cell growth and promotes cell senescence." (PMID 26257076, 2015). "At about the same time as the publication of our study, a Korean group reported a similar observation that Orai1 is overexpressed in tumor tissues from patients with ccRCC." (PMID 25481035, 2015).
tumor (continued). "To elucidate the function of SOCE in modulating the TME and tumor-associated macrophages (TAM, M2 phenotype), we tested the effect of STIM1 and ORAI1 on recruitment U937, a human leukemic monocyte macrophage cell line, in both DU145 and PC3 cells." (PMID 26257076, 2015). "Further studies of the mechanisms through which the Orai1 channel of cultured ESCC cells is activated are warranted in order to approach an understanding of the nature of ESCC tumor growth in vivo." (PMID 24797725, 2014). "In summary, this study demonstrated that tumor tissues from patients with ESCC express Orai1 at high concentrations; expression of the channel correlates closely with the recurrence rate for this disease independently of other factors." (PMID 24797725, 2014). "In 72 of 82 paired samples (88%), Orai1 expression was clearly higher in tumor tissues than in neighboring normal tissues." (PMID 24797725, 2014). "The functional significance of STIM1 and Orai1 in tumor progression in vivo has been revealed in breast and cervical cancer." (PMID 23594099, 2013). "Patients with loss-of-function mutations in the CRAC channel genes ORAI1 or STIM1 are immunodeficient and are prone to develop virus-associated tumours." (PMID 23922331, 2013). "Mouse models have shown that STIM1 and Orai1 expression is critical for breast cell tumour migration and metastasis." (PMID 24000152, 2013). "Knockdown of either SPCA2 or Orai1 expression was found to attenuate Ca2+-signaling and inhibit tumor growth in mouse xenografts." (PMID 23840669, 2013). "Similarly, in NSCLC, silencing the ORAI1 channel in tumor cells decreased PD-L1 exosome secretion, enhanced CD8+ T cell infiltration, and inhibited tumor progression." (PMID 39724442, 2024). "In studies on NSCLC, researchers found that the ORAI1 calcium channel could regulate intracellular calcium concentration and affect the secretion of exosomes carrying PD-L1 immune molecules produced by tumour cells." (PMID 38302430, 2024). "There are many reports that Orai1 regulates tumor growth, cell migration, metastasis and EMT." (PMID 37759164, 2023). "The Orai1 mutant (E106Q) inhibited xenograft tumor formation in the nude mice." (PMID 37759164, 2023). "Orai1-mediated SOCE is critical for tumor cell migration and metastasis." (PMID 33386992, 2021). "Regulators of cellular Ca2+ homeostasis, including ORAI1 (Calcium Release-Activated Calcium Channel Protein 1), STIM1 (Stromal Interaction Molecule 1), and TRP (Transient Receptor Potential) channels, are implicated in tumor cell migration and an aggressive cell phenotype." (PMID 34988012, 2021). "Another study reveals that Orai1 mediated SOCE are essential for tumor invasion in glioblastoma." (PMID 34012400, 2021). "The authors speculated that the increase in Orai3 expression and/or change in the tumour microenvironment (arachidonic acid) led to the recruitment of Orai1 subunits into the assembly of heteropentameric Orai1/Orai3 ARC channels." (PMID 32825277, 2020). "In ESCC, elevated expression of Orai1 in tumors was associated with poor prognosis, and its inhibition in cell lines by siRNA or drugs reduced SOCE and suppressed proliferation, invasion, and growth of tumor xenografts." (PMID 32575848, 2020). "Finally, the function of ORAI1 as an effector of RAC1 that has been shown here is particularly important since RAC1 drives tumor initiation." (PMID 32313105, 2020). "In addition, we have recently demonstrated another new functional coupling between Kv10.1 and Orai1, mediating the communication of the cells with the tumor microenvironment in BC16." (PMID 30718673, 2019). "Therefore, STIM1/Orai1-mediated Ca2+ machinery is a potential molecular target for strategies against tumor neovascularization." (PMID 31252656, 2019). "These highlight the clinical significance of STIM1 and Orai1 in tumor progression." (PMID 31252656, 2019).